GSTCD (glutathione S-transferase C-terminal domain containing)
Synonyms: FLJ13273
Tractability: PROTAC: ubiquitination databases record sites on it.
Gene: Protein-coding gene on chromosome 4 (105,708,778 to 105,849,570, forward strand). Ensembl gene ENSG00000138780.
Subcellular location: Cytoplasm
Subcellular location (Human Protein Atlas): Nucleoplasm
Gene Ontology:
Molecular function: protein binding
Cellular component: cytoplasm; extracellular exosome; nucleoplasm
Genetic constraint (gnomAD): Loss-of-function variants: 30 observed, 49.02 expected, observed/expected ratio (o/e) 0.61, 90% interval 0.46 to 0.83. The upper end of that interval is the gene's LOEUF score, 0.83, which puts it in group 3 of 6, group 1 being the genes least tolerant of losing a copy. Missense variants: 610 observed, 646.83 expected, observed/expected ratio (o/e) 0.94, 90% interval 0.88 to 1.01. Synonymous variants: 234 observed, 232.47 expected, observed/expected ratio (o/e) 1.01, 90% interval 0.9 to 1.12.
Homologues: Orthologues: chimpanzee GSTCD (99% identical), macaque GSTCD (98% identical), dog GSTCD (91% identical), rabbit GSTCD (90% identical), guinea pig GSTCD (86% identical), mouse Gstcd (85% identical), pig GSTCD (83% identical), rat Gstcd (80% identical), tropical clawed frog gstcd (63% identical), zebrafish gstcd (54% identical), Drosophila melanogaster CG10428 (32% identical).
Diseases named in the same sentence as GSTCD in open-access papers:
GSTCD is named in the same sentence as 9 diseases in open-access papers, as found by Europe PMC text mining. Sharing a sentence is not in itself a finding about the gene and the disease. The quoted sentences say what the papers report.
Hypertension (2 papers, 2014 to 2023). The presence of chronic increased pressure in the systemic arterial system. "We aimed to investigate effects of long-term traffic-related air pollution exposure, as well as variants in GSTP1, GSTT1 and GSTCD, on risk of acute myocardial infarction (AMI) and hypertension." (PMID 24915237, 2014). "This study shows significant association of vehicle air pollution exposure with risk of AMI; effects of variants in the GSTP1 gene on risk of hypertension, and suggests interactions between variants in the GSTP1, GSTT1 and GSTCD genes and vehicle air pollution exposure on risk of AMI." (PMID 24915237, 2014).
Airway obstruction (1 paper, 2013). Obstruction of conducting airways of the lung. "Existing evidence suggests that transcript levels of GSTCD are associated with variability in lung function from a study that investigated lung mRNA expression levels among individuals with variable degrees of airway obstruction." (PMID 24058608, 2013).
chronic obstructive pulmonary disease (1 paper, 2023). A chronic and progressive lung disorder characterized by the loss of elasticity of the bronchial tree and the air sacs, destruction of the air sacs wall, thickening of the bronchial wall, and mucous accumulation in the bronchial tree. "GSTCD has been implicated in the development of Chronic Obstructive Pulmonary Disease." (PMID 37627305, 2023).
periodontitis (1 paper, 2022). An acute or chronic inflammatory process that affects the tissues that surround and support the teeth. "In our study, gene expression of GSTCD in gingiva from periodontitis individuals was significantly increased in the GSE10334 (logFC=5.58) and GSE16134 (logFC=5.57) datasets compared with healthy populations, which is consistent with our TMT proteomics results." (PMID 36016933, 2022).
type 1 diabetes mellitus (1 paper, 2021). A chronic condition characterized by minimal or absent production of insulin by the pancreas. "We found multiple genomic variants in GSTCD, SKAP2, SLC9B1 and BANK1 genes to be present at a relatively higher frequency in our patient cohort indicating a causal connection between these variants and the incidence of type 1 diabetes mellitus in Qatar." (PMID 34556755, 2021).
infection (1 paper, 2021). The state of being infected such as from the introduction of a foreign agent such as serum, vaccine, antigenic substance or organism. "In this study, after the injection of NAC oxidative stress levels were significantly reduced in the pathogen infection group and the mRNA levels of SOD, CAT, GSTCD, and GSTO1 increased significantly." (PMID 33574492, 2021).
GSTCD also shares sentences with these, for which no sentence is quoted: acute myocardial infarction (1 paper); asthma (1); respiratory disease (1).